FADS2 (fatty acid desaturase 2)
Diseases named in the same sentence as FADS2 in open-access papers (continued):
Sharing a sentence is not in itself a finding about the gene and the disease.
cancer (continued). "Besides, FADS2 correlated with the majority of tumor-infiltrating immune cells (especially CAFs), immunoregulatory genes, and chemokines, revealing potential cancer-promoting mechanisms of FADS2." (PMID 36788618, 2023). "For instance, the fatty acid desaturase 2 (FADS2) pathway, an alternative FA desaturation pathway bypassing stearoyl-CoA desaturase 1 (SCD1), can cause an abnormal and elevated amount of n-10 isomers, adding to cancer plasticity." (PMID 36951803, 2023). "Increased FADS2 expression has been observed in certain cancers and may offer a mechanism of increased metabolic plasticity, suggesting increased FADS1 and/or FADS2 activity may result in therapeutic resistance in relapsed AML." (PMID 37110126, 2023). "Moreover, recent evidence showed that KRAS mutant cancer cells are also able to desaturate palmitate to sapienate via fatty acid desaturase 2 (FADS2), an event that confers additional independence to SCD-mediated FA desaturation." (PMID 36675307, 2023). "Accordingly, FADS2 could serve as a prognostic marker for pan-cancer and a biomarker for cancer immunologic infiltration." (PMID 36788618, 2023). "Numerous prior research has been carried out on the molecular function of FADS2 for cancers." (PMID 36788618, 2023). "As a result of these findings, it is concluded that FADS2 is frequently overexpressed in the majority of tumors and that its expression level and genetic alteration are significantly related to the prognosis of cancer patients." (PMID 36788618, 2023). "FADS2 has become a promising drug target in the treatment of cancers." (PMID 35401213, 2022). "Interestingly, we have previously identified an alternative fatty acid mono-desaturation pathway in cancer, mediated by the delta-6-desaturase FADS2, which produces the unusual fatty acid sapienate from palmitate." (PMID 36338708, 2022). "Furthermore, FADS2 knockdown suppressed cell invasion, another important property of cancer metastasis, by 2-fold." (PMID 37849907, 2021). "FADS2 may also contribute to production of a much wider spectrum of FAs in cancer cells as compared with their normal counterparts." (PMID 34206240, 2021). "However, not all cancer cells are responsive to SCD inhibition, and a recent study demonstrated FADS2 as an alternative desaturation pathway in SCD-independent cancer cells." (PMID 37849907, 2021). "Given the pro-tumoral roles of perturbed lipid metabolism in cancers, a dual inhibition of the proteasome and FADS2 could enhance the potency of proteasome inhibitors in solid cancers." (PMID 32851475, 2021). "A recent study found that cancer cells can bypass SCD by using FADS2 for fatty acid desaturation." (PMID 32103057, 2020). "Notably, FADS2 activity has been recently implicated in cancer plasticity and FADS2 inhibition with SC26196 impaired cancer stemness, NFκB signaling, and tumor initiation capacity." (PMID 32577235, 2020). "Inhibition of both desaturases, SCD and FADS2, resulted in reduced cancer growth in vivo, suggesting that targeting of multiple pathways may be needed in order to effectively impair cancer metabolic plasticity." (PMID 31922096, 2019). "However, recent evidence suggests that sapienate biosynthesis, through fatty acid desaturase 2 (FADS2), enables cancer cells to bypass the requirement for SCD1." (PMID 31344914, 2019). "Additionally, cancer cells also use an alternative desaturation pathway involving the FADS2 (fatty acid desaturase 2)-dependent desaturation of palmitate to sapienate (cis-6-C16:1) to support the synthesis of specific lipids and cellular membranes during proliferation." (PMID 40723225, 2025). "The previously unknown risk loci are implicated in cancer development and progression (e.g. CDKL1), pigmentation (e.g. TPCN2), cardiometabolic (e.g. FADS2), and immune-regulatory pathways for innate immunity (e.g. IFIH1), and HIV-1 viral load modulation (e.g. CCR5)." (PMID 36496446, 2022).
cancer (continued). "Collectively, this study suggests that harnessing inhibitors of SCD1 and FADS2 to selectively remove ascites-derived cancer cells could be a promising chemotherapeutic regimen to eradicate peritoneal metastases of OvCa and exhibited no cytotoxicity in normal cells and in vivo." (PMID 35547771, 2022). "In several cancer cell lines, FADS2 encoded Δ6 and Δ8 desaturation is not functional." (PMID 22140540, 2011). "Since PUFAs cannot be synthesized de novo, mesenchymal cancers regulate the ratio of PLs with PUFAs and MUFAs by upregulating ACSL4, fatty acid desaturase 2 (FADS2), and ELOVL fatty acid elongase 5 (ELOVL5)." (PMID 41596341, 2026). "Given the role of aberrant DNA methylation in cancer-related dysregulation, the UALCAN database was utilized to investigate the relationship between the expression patterns of ADAMTS3, FADS2, and RTBDN and methylation levels in both normal and tumor tissues." (PMID 40861806, 2025). "A549 cells, an SCD1 inhibitor-resistant cancer cell line, underwent ER stress-dependent cancer cell death upon dual inhibition of SCD1 and FADS2." (PMID 38849435, 2024). "This is also reflected by the correlation (ELOVL5, FADS2 and ACSL4) and anti-correlation (FASN and SCD) of these enzymes with Zeb1 expression in cancer cell lines." (PMID 39009641, 2024). "Additionally, FADS2-related gene enrichment analysis and immune infiltration analysis provide evidence of FADS2's potential role in regulating tumor immunity and indicate FADS2 can serve as a potential prognostic and immunotherapeutic biomarker for patients with cancers." (PMID 36788618, 2023). "Therefore, FADS2 may become a potential therapeutic target for cancer treatment." (PMID 36788618, 2023). "Some cancers rely on two desaturation pathways mediated by stearoyl-coenzyme A desaturase (SCD) and FADS2 to generate unsaturated fatty acids." (PMID 36147318, 2022). "Compared to the parental cancer cells, FASN, SCD1 and FADS2 expression at the mRNA and protein level consistently downregulated in the GFPT1 and OGT knockdown cells." (PMID 35844792, 2022). "Fatty acid desaturase 2 (FADS2), a key enzyme of polyunsaturated fatty acid (PUFA) metabolism, was involved in multiple diseases including cancer." (PMID 35027921, 2021). "Increased expression of FADS2 in tumors, including CRC, has been proposed to promote cancer cell proliferation in vitro, and tumor growth." (PMID 34206240, 2021). "They showed that some types of cancer cell are insensitive to modifications of SCD and continued to grow implicating a second enzyme FADS2." (PMID 31717414, 2019). "This breakthrough discovery sheds new light on the idea of targeting desaturation pathways in cancer cells, and suggests that only combined inhibition of SCD and FADS2 can become a fully effective way of treating certain types of cancer." (PMID 31284458, 2019). "Conversely, SCD1-resistant cancer cells did not undergo ER stress response-induced cell death because fatty acid desaturase 2 (FADS2) eliminated the accumulation of palmitic acid." (PMID 38849435, 2024). "This study may also contribute to the development of more effective cancer therapies through the inhibition of multiple enzyme targets, e.g., SCD1, FADS2, and CPT1, to minimize cancer recurrence and metastasis." (PMID 36951803, 2023). "Though increasing numbers of studies has explored the potential role of FADS2 in the progression and treatment of cancer over the past decade, systematic pan-cancer studies are still lacking to fully demonstrate its oncogenic impact and prognostic value." (PMID 36788618, 2023). "The enzymes in the VL-PUFA synthesis pathway, including ELOVL5, FADS2, and HSD17B12, can affect cellular arachidonic acid level and PGE2 level, and thus could change the biological activities of cancer cells in multiple stages." (PMID 36970499, 2023).
cancer (continued). "Given their consistent down-regulation, and the fact that FADS2 was found down-regulated after combinational treatment of selinexor and carfilzomib, we tested whether FADS2 and HERC4 play a role in carfilzomib’s anti-cancer effects." (PMID 32851475, 2021). "The mRNA levels of ELOVL4, ELOVL5 and FADS2 were increased in cultured cancer cells comparing to normal colon cells, but we did not detected the expression of ELOVL2 and FADS1 in these cells." (PMID 32029824, 2020). "The mRNA levels of ELOVL4 and 5, as well as FADS2 were higher in cancer cells than in normal colon cells, but we did not detected the expression of ELOVL2 and FADS1 in these cells." (PMID 32029824, 2020). "Therefore, for these types of cancer, only the combination therapy of SCD inhibitors and FADS2 inhibitors can block all compensatory pathways for tumor cells to acquire desaturated FAs, leading to impaired proliferation of tumor cells both in vitro and in vivo." (PMID 41421797, 2025). "Indeed, of the eight CRC GWAS loci found within this subset of CRC-related smoking genes, CDCA8, CDKN3, FADS1, FADS2, MYBL2, PCSK9, and PRC1, have all been reported to be overexpressed in others cancers and to play important roles in the DNA damage response pathway." (PMID 37509213, 2023). "Based on the expression of these three genes, the cancer cell clusters could be subdivided into SCD high [SCD-Hi (SC 6)], FADS2 high [FADS2-Hi (SC 17)], FASN high [FASN-Hi (SC 11)], SCD/FADS2/FASN high, [Triple-Hi (SC 7)] and SCD/FADS2/FASN low [Triple-low (SC 8)] cancer cells." (PMID 36338708, 2022). "Levels of TFRC (P<0.001), PHKG2 (P=0.005), FADS2 (P<0.001), and NOX1 (P=0.011) mRNA relative expression were higher in cancer cells than in immune cells, whereas levels of ALOX5 (P<0.001) mRNA relative expression were lower in cancer cells than in immune cells." (PMID 35866375, 2022). "However, there is no unified conclusion about the relationship of FADS2 with the proliferation or growth of cancer cells." (PMID 34095228, 2021). "However, according to the authors’ knowledge, no FADS1 or FADS2 inhibitors in cancer treatment are undergoing clinical trials." (PMID 32013225, 2020). "However, not all cancers exhibit sensitivity to SCD inhibition, as some tumor cells rely on compensatory desaturation pathways that utilize FADS2 to generate sapienate from palmitate esters." (PMID 41421797, 2025). "The increased TFRC, PHKG2, FADS2, NOX1, and reduced ALOX5 levels in LUSC tissues were reported in the present study, and scRNA-seq analysis showed that the levels of the five dysregulated genes were mainly influenced by cancer cells rather than immune cells." (PMID 35866375, 2022). "FADS2 converts them into arachidonic acid and, interestingly, palmitate can compete with linoleic and alpha-linoleic acids in this reaction, which could explain the ability of FADS2 to compensate for the lack of SCD activity in cancer cells." (PMID 40404984, 2025).
tumor (61 papers, 2012 to 2026). "Genomic and transcriptional alterations in this axis, including amplifications at 11q12-13 (housing FADS1–FADS3) and FADS2-derived circular RNAs, are associated with tumor aggressiveness and poor prognosis." (PMID 41465101, 2025). "The association between SCD or FADS2 expression and tumor-infiltrating immune cells (B cells, CD8+ T cells, CD4+ T cells, macrophages, neutrophils, and dendritic cells) in BRCA was determined using the TIMER tool." (PMID 38905386, 2024). "Overall, this study provides an in-depth understanding of the heterogeneity and complexity of the molecular biological characteristics of SCD and FADS2 by analyzing the prognosis, mutations, and tumor immune microenvironment in BRCA." (PMID 38905386, 2024). "EPIC, MCPcounter, XCELL, and TIDE were implemented to explore the association between FADS2 expression and CAFs infiltration in distinct tumor tissues." (PMID 36788618, 2023). "In summary, the association of FADS2 with increased risk of progression and death in the majority of tumors suggested a tumor-promoting role." (PMID 36788618, 2023). "In various tumor tissues, 77 FADS2 mutations were detected, including 60 missense mutations, 6 truncating mutations, 6 splice mutations, and 4 SV/fusion mutations and 1 in-frame mutation." (PMID 36788618, 2023). "Functional studies revealed that SCD1/FADS2 were positively associated with cell proliferation, cell migration, and tumor growth of OvCa cells while suppressed G1/S cell cycle arrest, oxidative stress, and cell death in the lipid-enriched microenvironment." (PMID 35547771, 2022). "Intriguingly, SCD and FADS2 have recently been implicated to involve in the inhibition of ferroptosis and are associated with tumor infiltration of some immune cells, such as dendritic cells (DCs) and B cells, whose expression levels can be used to predict prognosis and disease-free survival." (PMID 38459004, 2024). "Besides, the relationship between FADS2 and survival prognosis, clinicopathologic features, tumor-infiltrating immune cells, immunoregulatory genes, chemokines, chemokines receptor, tumor mutational burden (TMB), and microsatellite instability (MSI) was also explored." (PMID 36788618, 2023). "Intriguingly, in silico analysis of the Cancer Genome Atlas (TCGA) showed that SCD1 and FADS2 were the major isoforms and were highly expressed in tumor tissues, and were associated with poor overall survival (OS), advanced stage (Stage IV), and tumor recurrence in OvCa." (PMID 35547771, 2022). "FADS2, a member of the fatty acid desaturase family, is a key enzyme in the synthesis of polyunsaturated fatty acids (PUFAs), playing a vital role in tumour progression and chemotherapy resistance." (PMID 40682485, 2025). "ADAMTS3 and FADS2 exhibited downregulation in tumor tissues compared to normal lung tissues, whereas RTBDN displayed an opposite trend." (PMID 40861806, 2025). "The authors observed that FADS2 expression was significantly lower in the tumor tissue compared to the peritumoral area, suggesting tumor-specific metabolic adaptation." (PMID 40430008, 2025). "The results revealed that FADS2 knockdown significantly reduced both the weight and volume of the tumours compared to the control group." (PMID 40682485, 2025). "Desaturases such as stearoyl-CoA desaturase (SCD) and fatty acid desaturase-2 (FADS2) are frequently dysregulated across tumor types." (PMID 41465101, 2025). "The expression levels of key enzymes involved in unsaturated fatty acid metabolism (Fads2, Elovl5, Fads1, Elovl2) were significantly altered in the liver and tumor tissues of the HUFA-gavaged mice." (PMID 39941731, 2025). "In vivo, a mouse xenograft model confirmed that tumour volume and weight were significantly reduced when FADS2 expression was low." (PMID 40682485, 2025). "FADS2, has opposite effects on ferroptosis in various cancers, which is a double-edged sword in the regulation of tumor onset and development." (PMID 38459004, 2024).
tumor (continued). "An indirect support of this view comes from our findings that high expression of FADS2 in undifferentiated tumours (high-grade, mesenchymal subtype) correlates with better survival and particularly distant-metastasis-free survival." (PMID 39009641, 2024). "In these cells FADS2 desaturates the FA palmitate into the unusual the FA sapienate, which supports tumor cells’ membrane biosynthesis during proliferation." (PMID 39337514, 2024). "Dysregulation of the key enzyme FADS2 also directly interferes with fatty acid biosynthesis by tumor cells, which can hinder tumor progression." (PMID 36788618, 2023). "Apart from CHOL and uterine carcinosarcoma tumor tissues, more than 2% of SKCM, UCEC, MESO, ESCA, and COAD tumor tissues showed genomic alteration of FADS2." (PMID 36788618, 2023). "It has also been shown that overexpression of FADS2 andAP002754.2 accelerates tumor growth in in vivo experimentsin mice." (PMID 37965371, 2023). "There is evidence that fatty acid desaturase 2 (FADS2) is a crucial enzyme in tumor cells involved in lipid metabolism." (PMID 36788618, 2023). "In single-cell levels, FADS2 expression had a positive relationship with tumor biological behaviors such as inflammation, cell cycle, proliferation, DNA damage, and DNA repair response in tumors." (PMID 36788618, 2023). "FADS2 expression had a positive relationship with tumor biological behaviors such as inflammation, cell cycle, proliferation, DNA damage, and DNA repair response in tumors." (PMID 36788618, 2023). "At the protein level, FADS2 was positively linked to an advanced stage and higher histological grading in RCC, UCEC, LUAD, HNSC, and PAAD tumor tissues." (PMID 36788618, 2023). "In tumor tissues of BLCA, ESCA, KICH, and PAAD, high FADS2 expression was rather associated with the advanced pathological stages." (PMID 36788618, 2023). "FADS2 had a positive relationship with tumor biological behaviors such as inflammation, cell cycle, proliferation, DNA damage, and DNA repair response in single-cell levels." (PMID 36788618, 2023). "Heretofore, the precise mechanism of how FADS2 exerts its tumor-promoting function and the effects on the tumor immunological microenvironment is still unclear." (PMID 36788618, 2023). "Collectively, these results suggest that activated SCD1/FADS2 is required for aggressive tumor initiative potential, and UFA-mediated membrane fluidity is crucial for maintaining OvCa cell stemness within the ascites microenvironment." (PMID 35547771, 2022). "As PGE2 is responsible for radioresistance and temozolomide (TMZ) resistance, the enzymes involved in the synthesis of arachidonic acid C20:4n-6—in particular, Elovl5 and Fads2/D6D—are also responsible for the resistance to GBM anti-tumor therapy." (PMID 36291290, 2022). "The expression of FADS2 protein was significantly enhanced in tumour tissues as compared with adjacent normal tissues (p < 0.001, n = 16)." (PMID 35145965, 2022). "Instead of relying on the canonical SCD pathway for fatty-acid desaturation, tumor cells appear to exploit a different enzyme, FADS2, and upregulate this alternative route when SCD is inhibited." (PMID 35883589, 2022). "Patients overexpressing fatty acid desaturase 2(FADS2) in the tumor tissues had significantly shorter survival compared to the FADS2 low group." (PMID 35818395, 2022). "Some studies have found that FADS2 expression is significantly lower in tumour tissue than in normal samples." (PMID 34095228, 2021). "We also found that both FADS1 and FADS2 were significantly upregulated in the organoid rim region and corresponding cellular tumor regions in patient tumors." (PMID 34059134, 2021). "In the xenograft model, measurements of ferrous ion levels in tumour tissues revealed a significant increase following FADS2 knockdown, further supporting the hypothesis that reduced FADS2 expression promotes ferroptosis." (PMID 40682485, 2025).